MMP9 (matrix metallopeptidase 9)
Diseases named in the same sentence as MMP9 in open-access papers (continued):
Sharing a sentence is not in itself a finding about the gene and the disease.
gastric cancer (continued). "We found that ectopic expression of MICAL2 in gastric cancer cells increased MRTF-A accumulation in the nucleus, which was accompanied by enhanced MMP9 transcription and CDC42 activation." (PMID 33842533, 2021). "In conclusion, these results suggest that muscone exerts antitumor effects in vitro against the gastric cancer cell line SGC‐7901 via a pathway involving PI3K, AKT, c‐Myc, MMP‐2, and MMP‐9." (PMID 34531985, 2021). "M2 macrophages expressing the surface markers CD206 and CD204 promote the invasion and migration of gastric cancer cells by stimulating VEGF and MMP9 expression in cancer cells." (PMID 33867855, 2021). "Studies have also shown that the migration and invasion of human gastric cancer cells SGC7901 can be inhibited by the P38MAPK signaling pathway through the expression of MMP-2 and MMP-9." (PMID 34127929, 2021). "For gastric cancer in particular, CORO3 has been observed to promote cancer metastasis by upregulating the expression levels of MMP9 and cathepsin K." (PMID 34026752, 2021). "In the case of gastric cancer, a positive correlation between the concentration of the VEGF and MMP-2 and also VEGF and MMP-9 was found." (PMID 32594304, 2021). "In gastric cancer, upregulation of TMPRSS4 facilitates cell migration and invasion through the activation of NF-κB/MMP-9 signaling." (PMID 32695668, 2020). "WISP2 regulated cell growth, migration, and metastasis by regulating EMT and inhibiting matrix metalloproteinase (MMP)-9 and MMP-2 via ERK in gastric cancer cells." (PMID 32711570, 2020). "In gastric cancer, SNHG15 upregulation promotes cell proliferation and invasion by modulating the expression of MMP2/MMP9." (PMID 33243205, 2020). "Naringenin can significantly inhibit the growth of human gastric cancer cells (SGC-7901), reduce the expression of MMP-2 and MMP-9 in gastric cancer cells, and significantly suppress the proliferation, adhesion, invasion, and migration of SGC-7901." (PMID 33265939, 2020). "Next, the results of western blot indicated that peritoneal mesothelial cells significantly increased the protein expressions of MMP3, MMP9 and PCNA in metastatic gastric cancer cells, especially peritoneal metastatic gastric cancer cells." (PMID 32139657, 2020). "For gastric cancer, SOX9 was identified as a critical determinant in the control of epithelial-to-mesenchymal transition (EMT) and metastasis via affecting MMP-2 and MMP-9." (PMID 33076370, 2020). "The neutrophils secrete matrix metalloproteinase-9 (MMP9) at cancer invasive margin, which play a crucial role in proangiogenic activity in gastric cancer." (PMID 32411209, 2020). "Subsequent studies have shown that gastric cancer cells infected by Helicobacter pylori increase the activity of MMP-2, MMP-9, and MMP-10 through c-Met- and EGFR-dependent signaling pathways, inducing ECM remodeling and cell invasion." (PMID 32046329, 2020). "In summary, FBN1, FN1, HGF, MMP9, THBS1, and VCAN can be used as new target genes to observe the prognosis of gastric cancer." (PMID 33014013, 2020). "In gastric cancer cells, activated c‐Src can increase MMP‐2 and MMP‐9 expression and the degradation of the ECM, and play the role of VEGF‐C, thereby increasing the ability of gastric cancer cell metastasis through a series of processes." (PMID 31957271, 2020). "For instance, MMP-9 expression was markedly higher in gastric carcinoma tissues than in adjacent healthy tissues, and associated with the depth of cancer invasion, suggesting that MMP-9 may serve as a novel biomarker in the diagnosis and prognosis of gastric carcinoma." (PMID 32046329, 2020). "In order to understand gastric cancer further, we investigated the effects of LOX on MMP-2 and MMP-9 and its mechanisms in this disease." (PMID 31777578, 2019). "We analyzed the protective effect of LPE on IL-6-induced migration/invasiveness or MMP-9/2 up-regulation in MKN-28 and AGS gastric cancer cells." (PMID 31817563, 2019).
gastric cancer (continued). "We selected MMP9 as a potential VGLL1-targeted gene, because high MMP expression is correlated with metastasis and poor prognosis in gastric cancer." (PMID 31816819, 2019). "After LOX were inhibited with different concentrations of BAPN in BGC-823 gastric cancer cells, the protein concentrations and enzyme activity levels of MMP-2 and MMP-9 in the culture supernatants were decreased (P < 0.05)." (PMID 31777578, 2019). "WISP2 downregulation promoted cell growth, migration and invasion, but WISP2 overexpression suppressed cell metastasis through regulation of EMT and inhibition of MMP-9 and MMP-2 via ERK in gastric cancer cells." (PMID 30808397, 2019). "Mast cells exert a protumorigenic role in gastric cancer through the release of angiogenic (VEGF-A, CXCL8, MMP-9) and lymphangiogenic factors (VEGF-C and VEGF-F)." (PMID 31035644, 2019). "As cell invasiveness is strictly related to IL-6-induced upregulation of MMP-9 and MMP-2 expression levels in human gastric cancer cells, we have explored the effect of LPE in rIL-6 exposed MKN-28 and AGS cells." (PMID 31817563, 2019). "We found that Zey suppressed the metastasis of gastric cancer cells by decreasing protein levels of MMP-2 and MMP-9 and inhibiting the phosphorylation of AKT, ERK, and mTOR." (PMID 30150551, 2018). "The aim of this study is to determine the role of serum CK18, MMP-9, and TIMP1 levels in predicting R0 resection in patients with gastric cancer." (PMID 29651326, 2018). "Histone deacetylation was involved in the down-regulation of FENDRR in gastric cancer cells and FENDRR overexpression suppressed invasion and migration by down-regulating FN1 and MMP2/MMP9 expression." (PMID 29069754, 2017). "This study's findings suggest that in gastric cancer, AEG‐1 promotes EMT via eIF4E‐regulated MMP‐9 and Twist." (PMID 28661037, 2017). "RelA expression in gastric cancer tissue strongly correlated with abundance of other tumor- and metastasis-promoting markers, including STAT3, MMP-9, IL-6 and VEGF." (PMID 28350359, 2017). "The silencing of RELM-α expression by Ad5/F35-siRNA treatment significantly inhibited NF-κB activation and attenuated VEGF and MMP-9 expression as well as cell migratory and invasive ability in SGC7901 and MKN45 gastric cancer cells." (PMID 28350359, 2017). "We have validated that integrinβ6 promoted the invasion, metastasis and degradation of extracellular matrix of colorectal cancer, thyroid carcinoma, gastric carcinoma, and pancreatic carcinoma through up-regulation of MMP-3/MMP-9." (PMID 27835891, 2016). "OPN has been reported to promote invasion and metastasis of gastric cancer through HIF-1α upregulation and MMP9 activation." (PMID 25872762, 2015). "The mechanisms of NKD2 in gastric cancer cell invasion and migration were further investigated by detecting the expression of MMP-2 and MMP-9." (PMID 26396173, 2015). "Taken together, our results suggest that M2-like macrophages are more efficient than their M1 counterparts in stimulating gastric cancer cell invasion, likely due to their increased MMP-2 and MMP-9 activity and higher ability to promote cancer cell migration." (PMID 26043921, 2015). "FENDRR is down-regulated in gastric cancer, and decreased expression of FENDRR induces FN1 expression, which resulted in activation of MMP2/MMP9." (PMID 26238992, 2015). "We also found that the induction of FENDRR potently reduced the activity of MMP2/MMP9 in GC cells, and inhibition of FENDRR contributed to the activation of MMP2/MMP9, corroborating our earlier finding that FENDRR protected against gastric cancer cell metastasis." (PMID 25167886, 2014). "To better understand the clinical significance of ALDH1A1 on aggressiveness in gastric cancer, we investigated the relationship of ALDH1A1 and MMP-9 protein expression in gastric cancer." (PMID 25253129, 2014). "FENDER overexpression suppressed invasion and migration by gastric cancer cells in vitro, by downregulating FN1 and MMP2/MMP9 expression." (PMID 25167886, 2014).
gastric cancer (continued). "The bone morphogenetic protein signaling pathway enhances tumor invasiveness and metastasis in gastric carcinoma by sequential activation of PI3K/Akt followed by induction of NF-κB and MMP-9 activity." (PMID 25003395, 2014). "A synthetic small-molecule pan-PI3K inhibitor, LY294002, significantly inhibits the growth of gastric carcinoma while promoting apoptosis, resulting in the downregulation of MMP-2, MMP-9, and VEGF." (PMID 25003395, 2014). "In this study, we detected those metastasis relevant factors, including MMP7, MMP9 and MMP14, which are particularly important in gastric cancer." (PMID 24386080, 2013). "Here, we examined the MMP9 expression and found that both NF-κB and STAT3 activation were positively correlated with MMP9 expression in clinical gastric cancer samples and in cultured cells." (PMID 23402362, 2013). "In summary, our results indicate that elevated ADCY3 expression contributes to gastric cancer progression through the cAMP/PKA/CREB pathway, by increasing both mRNA expression and MMP2 and MMP9 activity." (PMID 24113161, 2013). "In vitro experiments showed that Mfn2 overexpression suppressed gastric cancer cell proliferation and colony formation, weakened the invasion and migratory ability of cancer cells by downregulating MMP-2 and MMP-9, halted the cell cycle and induced apoptosis." (PMID 23797661, 2013). "Silencing of HMGB1 expression by an HMGB1-specific RNAi lentiviral vector has been shown to reduce matrix metalloproteinase 9 (MMP9) expression and metastatic capacity in MGC-803 gastric carcinoma cells." (PMID 23378947, 2013). "Based on our results, it is possible that via the upregulation of Cyclin D1, EGFR, Bcl-2, MMP-9 and MMP-2 expression and MVD, CXCR1/2 and their ligands are involved in mediating proliferation, growth, angiogenesis, invasion and metastasis of gastric carcinoma." (PMID 23420470, 2013). "Taken together, these results suggest that MMP-9, TIMP-2 and cathepsin K at least partially contribute to coronin 3-mediated gastric cancer metastasis." (PMID 22974233, 2012). "Previous studies described MMP-9 in the pathogenesis of Barrett's esophagus, ESCC, and gastric cancer." (PMID 20946664, 2010). "In this study, real-time PCR was used to determine mRNA levels of MMP-2, MMP-7, MMP-9 and MT1-MMP in gastric cancers." (PMID 19586554, 2009). "Real-time reverse-transcription PCR was performed to determine the mRNA expression of some members in MMP family, including MMP-2, MMP-7, MMP-9 and MT1-MMP in 32 gastric cancer specimens and corresponding matched normal tissue specimens." (PMID 19586554, 2009). "The results showed that MMP-2, MMP-7, MMP-9 and MT1-MMP were all significantly upregulated in gastric cancer specimens compared to matched normal tissue specimens (For both MMP-2 and MMP-9, P < 0.01; for both MMP-7 and MT1-MMP, P < 0.001)." (PMID 19586554, 2009). "Overexpression of MMPs has been observed in a series of cancers, with that of MMP-2, MMP-7, MMP-9 and MT1-MMP, in particular, typically present in gastric cancer." (PMID 19586554, 2009). "Our initial finding showed that SFRP5 expression is significantly downregulated in gastric cancer, while the subsequent quantitative real-time PCR analysis revealed that MMP-2, MMP-7, MMP-9 and MT1-MMP are all upregulated in it." (PMID 19586554, 2009). "In conclusion, the present study demonstrate that AhR pathway can be activated in gastric cancer AGS cells and AhR pathway activation induces MMP-9 expression and activity which ultimately contributes to AGS migration and invasion in vitro." (PMID 19371443, 2009). "Second, some MMPs, such as MMP-2, MMP-7, MMP-9 and MT1-MMP, are frequenly overexpressed in gastric cancers, primarily in both tumor cells and stromal cells (except MMP-7, which is only expressed in tumor cells)." (PMID 19586554, 2009). "MMP-9 mRNA and protein expression was dose-dependently increased by TNF-α in SNU216 and SNU668 gastric cancer cells." (PMID 19924065, 2009).
gastric cancer (continued). "Our data presented here demonstrate that AhR pathway can be activated in gastric cancer AGS cells and AhR pathway activation in AGS cells induces MMP-9 expression and enhances AGS cells migration and invasion activity." (PMID 19371443, 2009). "MMP-2 (gelatinase A), MMP-9 (gelatinase B), MMP-7 (matrilysin) and MMP-14 (MT1-MMP) are over-expressed in human gastric cancer." (PMID 12085177, 2002). "Patients with gastric cancer had higher levels of the ADAM12 and MMP-9/NGAL complex in their urine." (PMID 40277747, 2025). "This discrepancy may be explained by concomitant upregulation of MMP9 and MMP14 in gastric cancer, where increased MMP14 expression correlates with metastasis and poor prognosis." (PMID 40643467, 2025). "The combined dose of harmine and paclitaxel resulted in a synergistic anti-cancer effect that, in turn, downregulated matrix metallopeptidase 9 (MMP-9) and cyclooxygenase 2 (COX-2) in the gastric cancer cell lines, reducing proliferation and leading to apoptosis." (PMID 39954215, 2025). "Furthermore, a study using a xenograft model with transplanted gastric cancer tissue has revealed that chronic stress stimulates the β-adrenergic receptor (ADRB), which leads to the overexpression of VEGF, MMP-2, MMP-7, and MMP-9 in transplanted tumor tissue." (PMID 40362226, 2025). "In this study, the potential target of HL-RG in the treatment of gastric cancer was studied Through PPI network analysis and molecular pairing, TGFB1, CCND1, MMP9, ERBB2, CAT, and PPARα may be the core targets of HL-RG in the treatment of RCC." (PMID 41305721, 2025). "The analysis suggests that the MMP9 and CASP3 genes may influence the overall survival (OS) in gastric cancer." (PMID 38769413, 2024). "Moreover, SNHG15 can promote the proliferation and invasion of gastric cancer cells by regulating the expression of MMP2 and MMP9 proteins." (PMID 38526609, 2024). "Similarly, sinulariolide, extracted from Sinularia flexibilis, has been shown to suppress MMP-2 and MMP-9 expression via the MAPK pathway in liver and gastric cancer cells, thereby diminishing cancer cell migration and invasion." (PMID 38374934, 2024). "MMP9 and CXCR4 were upregulated in gastric cancer in copy number analysis." (PMID 38457601, 2024). "For RUNX3, a tumor suppressor role has been reported in gastric cancer, contingently via a mechanism involving negative regulation of MMP9 and vimentin." (PMID 38630262, 2024). "In human gastric cancer cell lines, AQP3 induced expression of MT1-MMP, MMP2 and MMP9." (PMID 37681917, 2023). "In gastric cancer, 6-shogaol intervention in gastric cancer BGC-823 cells significantly affects the expression of EMT related proteins and regulates E-cadherin protein, MMP-2, and MMP-9." (PMID 37875983, 2023). "Further research yielded the development of drugs specifically against MMP9, and the effect of humanized monoclonal antibodies (ANDECALIXIMAB) against the enzyme has been studied in gastric carcinoma, which showed moderate efficacy when they were given in combination with other cytotoxic drugs." (PMID 36756017, 2023). "Previous studies reported that indirect co-culture between cancer cells and macrophages could upregulate MMP9 production in various cancer cell lines, including ovarian carcinoma, head and neck carcinoma, ESCC, gastric carcinoma, and fibrosarcoma cell lines." (PMID 37296952, 2023). "Upregulating the expression of MMP9 can reverse the inhibitory effect of lncRNA-PVT1 overexpression on LCC, while downregulating its expression can reverse the promotion of MMP9 silencing on gastric cancer cell migration." (PMID 36164442, 2022). "In gastric cancer, SIRT2, as a downstream target of miR-138, can increase PEPCK1-related metabolism, thereby promoting gastric cancer cell migration and invasion through the RAS/ERK/JNK/MMP-9 pathway." (PMID 36101744, 2022).
gastric cancer (continued). "Numerous soluble and membrane-anchored host proteases have been associated with E-cadherin shedding, such as the matrix metalloproteases MMP3, MMP7, MMP9, MMP14, ADAM10, and ADAM15, which are upregulated in response to H. pylori infection and in gastric cancer tissue." (PMID 35269560, 2022). "High MMP-9 expression is observed in tumor extracts in gastric cancer; furthermore, aberrant expression of MMP-9 can increase tumor cell detachment and metastasis, which are related to malignancy and poor prognosis in gastric cancer." (PMID 35563563, 2022). "The low expression of CDC2, VEGF, and MMP-9 might account for the inhibitory effects of WT and mutant ING5 on the proliferation and invasion of gastric cancer." (PMID 35747809, 2022). "Similarly, in human gastric carcinoma cells, upregulated AQP3 levels correlated with increased MMP2 and MMP9 expression, whereas AQP3 silencing reduced MMP2 and MMP9 expression." (PMID 35163313, 2022). "Biochemical molecular analysis revealed that TIPE2 could reduce the activation of RAC1 and MMP9 by binding to RAC1, thereby suppressing gastric cancer cell metastasis." (PMID 34630074, 2021). "The enrichment included the PI3K-Akt and IL-17 signaling pathways, and the network analysis showed that the Zhishi-Baizhu herb pair acted on seven key targets, namely, AKT1, MMP9, IL-6, CCND1, BCL2, MTOR, and MDM2 (where they played a role in treating gastric cancer)." (PMID 34899944, 2021). "Furthermore, MICAL2 facilitates gastric cancer cell migration by promoting MRTF-A-dependent activation of cell division control protein 42 homolog (CDC42) and expression of MMP9." (PMID 33842533, 2021). "Metastatic gastric cancer cell supernatant treatment significantly downregulated E-cadherin expression in peritoneal mesothelial cells, while it notably upregulated N-cadherin, α-SMA, Snail, Twist, Slug, Cyclin D1, MMP3 and MMP9 expression." (PMID 32139657, 2020). "Importantly, we found that Tid1 knockdown elevated the MMP-9 gene expression of MMP-9 in the AGS, NUGC-3, and TSGH9201 gastric cancer cells." (PMID 33233689, 2020). "Through detecting protein levels of c-Myc, Bax and MMP9 combined with corresponding analyses of MTT, flow cytometry and transwell, we found that LINC00483 knockdown suppressed gastric cancer development by inhibiting cell viability, migration and invasion and inducing apoptosis." (PMID 32293550, 2020). "MIR211 regulates Matrix metalloproteinase-9 (MMP-9) and thereby reduces EMT in gastric cancer." (PMID 33628737, 2020). "According to our previous studies, TSPAN9 regulates the protein secretion levels associated with tumor metastasis, such as matrix metalloproteinase-9(MMP-9) through the ERK1/2 pathway, thereby inhibiting gastric cancer cell proliferation, migration, and invasion." (PMID 31242895, 2019). "Simultaneously, we examined the expressions and activities of MMP-2 and MMP-9 after LOX inhibition and exogenous LOX treatment in gastric cancer cells, and analyzed the effect of LOX inhibition on PDGFR in the PDGF-PDGFR signaling pathway in gastric cancer cells." (PMID 31777578, 2019). "Gelatin zymography assay further indicated the activity of MMP2 and MMP9 was restrained by TIPE1 in BGC823 cells, which may partially explain that TIPE1 can inhibit migratory and invasive behaviours in gastric cancer cells." (PMID 28994231, 2018). "The upregulation of HSF1 in gastric cancer cells stimulates the expression of MMP2, MMP7 and MMP9." (PMID 30326922, 2018). "Furthermore, bufalin inhibited ASCL2 expression and down-regulated the expression of invasion-related genes such as MMP2, MMP9, and vimentin, thereby suppressing epithelial-mesenchymal transition (EMT) in gastric cancer." (PMID 29805736, 2018). "Besides, knockdown of SNHG15 significantly inhibited cell proliferation and invasion and promoted apoptosis, whereas forced expression of SNHG15 exhibited the opposite effects on gastric cancer cells via regulating MMP2 and MMP9 protein expression." (PMID 28720111, 2017).